NLRP6 (NLR family pyrin domain containing 6)
Diseases named in the same sentence as NLRP6 in open-access papers (continued):
Sharing a sentence is not in itself a finding about the gene and the disease.
Sepsis (10 papers, 2022 to 2025). Sepsis is defined as life-threatening organ dysfunction caused by a dysregulated host response to infection. "Taken together, our data implicated that the NLRP6 inflammasome serves as a negative regulator of host protection in sepsis." (PMID 38720893, 2024). "The NLRP6 inflammasome triggers a destructive inflammatory response and enhances sepsis-induced loss of lymphocytes." (PMID 38720893, 2024). "NLRP6 has been identified as a key regulator of neutrophil recruitment, generation, and function during bacterial pneumonia and septicemia in the mouse model of pneumonia-derived septicemia caused by Klebsiella pneumonia." (PMID 37415625, 2023). "However, we have recently shown that NLRP6 is a positive regulator of neutrophil recruitment and function during K. pneumoniae-induced pneumonia-derived sepsis where the NLRP6-deficient mice had reduced survival, increased bacterial burden, and decreased neutrophil migration and function." (PMID 37662905, 2023). "It is found that NLRP6 is a key regulator of neutrophil production and recruitment during sepsis after bacterial pneumonia in NLRP6 knockout mice infected with Klebsiella pneumoniae." (PMID 40837366, 2025). "We have used NLRP6 KO mice and human septic spleen samples to examine the role of NLRP6 in host defense in sepsis." (PMID 38720893, 2024). "Genetic disruption of NLRP6 enhances the survival during CLP-induced polymicrobial sepsis and E. coli-induced sepsis models." (PMID 38720893, 2024). "Co-housed WT and NLRP6 KO mice following sepsis show decreased bacterial burden in KO mice similar to without co-housing." (PMID 38720893, 2024). "Here, we have used human septic spleen samples and a murine model of cecal ligation and puncture (CLP)-induced polymicrobial sepsis to study the detailed mechanisms by which NLRP6 regulates host defense." (PMID 38720893, 2024). "Although NLRP6 is well expressed in several organs including intestine, kidney, liver, and lung, its potential roles in sepsis remain elusive." (PMID 38720893, 2024). "Reduction in IL-1β in the PF of KO mice compared to WT mice indicates that the NLRP6 inflammasome is activated during sepsis." (PMID 38720893, 2024). "Overall, the current study uncovered a previously unrecognized role of the NLRP6-IL-18 axis during sepsis." (PMID 38720893, 2024). "Next, to investigate the role of NLRP6 in sepsis, we induced moderate sepsis in NLRP6 KO and WT mice through CLP." (PMID 38720893, 2024). "NLRP6 is a relatively newly identified member of the NLR family and acts as an inflammasome implicated in granulopoiesis, neutrophil recruitment and the formation of neutrophil extracellular traps (NETs) in bacterium-induced sepsis." (PMID 40624022, 2025). "However, in mice undergoing cecal ligation and puncture‐induced polymicrobial sepsis or E. coli‐induced sepsis, NLRP6‐mediated release of IL‐18 exacerbates sepsis." (PMID 39351983, 2025). "Loss of MMP7 could potentially attenuate sepsis-induced kidney injury through decreased activation of NLRP3 and NLRP6 inflammasomes in the kidney." (PMID 40341670, 2025). "According to these observations, we examined whether the NLRP6 inflammasome regulates lymphocyte death during sepsis." (PMID 38720893, 2024). "Furthermore, NLRP6 plays a detrimental role in host defense during sepsis through IL-18-mediated destructive inflammation." (PMID 38720893, 2024).
Sepsis (continued). "Based on these results, we propose that blocking NLRP6 could be an effective therapy to reduce sepsis-related mortality." (PMID 38720893, 2024). "In addition, we have shown that NLRP6-driven IL-18 enhances mortality in sepsis through mediating both inflammation and cell death." (PMID 38720893, 2024). "However, in the sepsis models, we found that the NLRP6 KO mice had reduced neutrophil recruitment, attenuated cytokine production, augmented bacterial clearance, and higher survival." (PMID 38720893, 2024). "Finally, we evaluated the mechanisms by which IL-18 enhances mortality in NLRP6 KO mice following sepsis." (PMID 38720893, 2024). "In addition, the PF obtained from septic KO mice displayed less LDH release compared to that of WT counterparts, indicating that NLRP6 enhances cell death during sepsis." (PMID 38720893, 2024). "Using CLP, we demonstrate that the NLRP6 inflammasome plays a detrimental role following sepsis." (PMID 38720893, 2024). "Therefore, we determined whether NLRP6 initiates hyperinflammation to enhance mortality during sepsis." (PMID 38720893, 2024). "However, the role of NLRP6 in polymicrobial sepsis remains elusive." (PMID 38720893, 2024). "The NLRP6 KO mice showed higher numbers of CD3-, CD4- and CD8-positive T cell subsets and decreased T cell death in the spleen following sepsis." (PMID 38720893, 2024). "Using human and animal samples, we have demonstrated that NLRP6 is upregulated in multiple cell types, including CD4 and CD8 T cells in the spleen during sepsis." (PMID 38720893, 2024). "We found that NLRP6-driven IL-18 but not IL-1β contributes to sepsis-induced lymphocyte death, which were found to be crucial for host defense." (PMID 38720893, 2024). "The co-housed KO mice displayed a similar phenotype as that of singly housed KO mice confirming that NLRP6 regulates sepsis independent of microbiota composition." (PMID 38720893, 2024).
viral infections (9 papers, 2011 to 2026). "Meanwhile, NLRP6 and NLRP9b were upregulated in mouse IECs from Trim29IEC-KO mice after virus infection owing to the loss of degradation by TRIM29." (PMID 39396665, 2025). "On contrast, NLRP6 and NLRP9b were upregulated in IECs of intestines from Trim29IEC-KO mice after virus infection owing to the loss of degradation by TRIM29 in vivo." (PMID 39396665, 2025). "TRIM29 was upregulated in IECs from intestines of Trim29fl/fl mice after EMCV or Rotavirus infection in vivo, whereas NLRP6 and NLRP9b were downregulated in IECs of intestines from Trim29fl/fl mice after virus infection owing to the degradation by TRIM29." (PMID 39396665, 2025). "TRIM29 was upregulated in primary IECs from mouse intestine organoids of Trim29fl/fl mice after EMCV or Rotavirus infection, whereas NLRP6 and NLRP9b were downregulated in mouse IECs from Trim29fl/fl mice after virus infection owing to the degradation by TRIM29." (PMID 39396665, 2025). "Specifically, NLRP6, highly expressed in the intestine, executes essential roles for intestinal mucosal self-renewal and proliferation also protecting the host against bacterial and viral infection." (PMID 38315242, 2024). "Thus, NLRP6 plays a protective role in the host against bacterial and viral infections in the intestine, where it is highly expressed." (PMID 33910012, 2021). "This comprehensive review synthesizes the diversified landscape of inflammasome activation during viral infections, extending beyond the canonical NLRP3 inflammasome to include specialized sensors such as NLRP6, NLRP9, NLRP1, NLRP12, and NLRC4." (PMID 42198749, 2026). "Additionally, considering NLRP6’s antiviral role in the intestines, it would be interesting to investigate if NLRP6 plays a protective or negative role in pulmonary host defense during viral infection." (PMID 38736751, 2024). "However, another study showed that loss of DHX15 has no impact on inflammasome activation during virus infection, suggesting a DHX15-independent manner of NLRP6 inflammasome activation." (PMID 36825215, 2022).
colon carcinoma (8 papers, 2013 to 2023). "Meanwhile, IL-18 silencing in NLRP6 deficient mice has been associated with increased colon cancer development, indicating the pivotal role of cytokines in mediating the anti-carcinogenic activities of NLRP6." (PMID 27206676, 2016). "Here, we report that NLRP6 is very faintly expressed in several colon cancer cell lines, detected only in cytoplasmic small dots were it colocalizes with ASC." (PMID 36662875, 2023). "In order to further study the role of NLRP6 in colorectal carcinogenesis, we transiently overexpressed the full length NLRP6 protein (NM_138329.2) with a C-terminal FLAG epitope in the human colon cancer cell lines HCT116 and RKO." (PMID 36662875, 2023). "It is possible that the mechanisms that regulate NLRP6 in colon cancer could be defective and require further investigation." (PMID 33910012, 2021). "Moreover, SCFAs-mediated NLRP6 inflammasome activation was inhibited by histamine (a bacterial metabolite) in ex vivo colonic explants and suppressed in murine CT26 colon carcinoma cells transfected with NLRP6 siRNA." (PMID 31255176, 2019). "Additionally, NLRP6 protein levels and IL-18 production were increased by SCFAs but decreased by NLRP6 siRNAs in murine CT26 colon carcinoma cells." (PMID 31255176, 2019).
liver disease (7 papers, 2020 to 2026). "Although the loss of NLRP6 NEMO other IKK components have not been described in human HCC, this mouse model nicely reflects essential mechanisms of human liver disease progression and allowed us to study the impact of intestinal dysbiosis induced by loss of NLRP6 on liver disease progression." (PMID 35803930, 2022). "NLRP6 regulates intestinal homeostasis and inflammation, but also is involved in cancer, the nervous system or liver diseases, with both protective and deleterious consequences." (PMID 35650327, 2022). "This review discusses emerging roles for the NLR family pyrin domain containing 6 receptor (NLRP6) in intestinal homeostasis, inflammation, cancer, the nervous system and liver disease." (PMID 35650327, 2022). "Several studies have suggested a protective role of NLRP6 in a variety of liver diseases, such as liver cirrhosis, liver injury, acute liver failure, and alcoholic hepatitis." (PMID 35659304, 2022). "Recently, other components of the inflammasome pathway, such as NLRP6, have been related to liver diseases and fibrotic processes." (PMID 32431709, 2020). "NLRP6 knockout mice show lesser degrees of alcohol-induced liver diseases." (PMID 37371502, 2023). "Intriguingly, NLRP6 inflammasome plays protective roles in alcohol-induced liver diseases." (PMID 37371502, 2023). "Finally, we asked whether liver disease progression could even be improved in the Nlrp6−/− dysbiosis model." (PMID 35803930, 2022). "Alcohol-mediated liver diseases are involved in various types of inflammasome including NLRP3, NLRP6, and NLRC4 inflammasomes." (PMID 37371502, 2023). "Together, these data demonstrate that the absence of NLRP6 orchestrates the inflammatory response in the tumor microenvironment and drives liver disease progression towards fibrosis and cancer in NEMO∆hepa/Nlrp6−/− mice." (PMID 35803930, 2022). "Upregulation of NLRP6 and IL-18 was also reported in adipose tissues obtained from NASH patients with portal fibrosis compared with that from control patients, suggesting a role of NLRP6 in liver disease." (PMID 33910012, 2021).
non-alcoholic fatty liver disease (7 papers, 2012 to 2026). "Previous work has studied the role of Nlrp3 and another member of the NLR inflammasome family, Nlrp6, in the context of nonalcoholic fatty liver disease (NAFLD)." (PMID 24453428, 2013). "In a mouse model of NAFLD (Nonalcoholic fatty liver disease), GW501516, a specific PPARβ/δ ligand, inhibited the activation of NLRP3, NLRP6, and NLRP10 and decreased the production of pro-inflammatory molecules induced by high fat diet and LPS." (PMID 34829605, 2021).
pneumonia (7 papers, 2018 to 2024). An acute, acute and chronic, or chronic inflammation focally or diffusely affecting the lung parenchyma, caused by an infection in one or both of the lungs (by bacteria, viruses, fungi, or mycoplasma.). "Our observations indicate that NLRP6 from both cell types contributes to the enhanced susceptibility to S. aureus-induced pneumonia." (PMID 30248149, 2018). "In a MRSA-induced pneumonia model, NLRP6 KO mice had higher neutrophil accumulation in the lungs due to reduced cell death." (PMID 38720893, 2024). "Of note, activation of the NLRP6 inflammasome during acute pneumonia negatively regulates pulmonary defenses, as NLRP6-/- mice accelerate neutrophil recruitment and display increased resistance to staphylococcal lung infection." (PMID 33552085, 2020). "In the current study, we demonstrate that NLRP6 is upregulated in neutrophils, macrophages, and epithelial cells in the lungs of human pneumonia patients." (PMID 30248149, 2018). "This suggests that NLRP6 enhances inflammatory modes of cell death during S. aureus-induced pneumonia." (PMID 30248149, 2018). "Next, we determined if NLRP6 expression is upregulated in S. aureus-induced pneumonia in mice." (PMID 30248149, 2018). "Since we found upregulation of NLRP6 in both hematopoietic (neutrophils and macrophages) and non-hematopoietic cells (epithelial cells), we sought to determine if NLRP6 from each of these compartments is detrimental to bacterial clearance of S. aureus-induced pneumonia." (PMID 30248149, 2018). "NLRP6 also limited ROS production and INF-γ after infection, which suggests that blocking NLRP6 could be a therapeutical approach for augmenting neutrophil-associated bacterial clearance and improving pneumonia." (PMID 35650327, 2022).
inflammatory bowel disease (6 papers, 2016 to 2026). A spectrum of small and large bowel inflammatory diseases of unknown etiology. "Furthermore, NLRP6 is linked to colorectal cancer and inflammatory bowel disease, as well as neuroinflammation." (PMID 41266655, 2026). "A wild-type microbiome can also protect NLRP6-deficient animals from inflammatory bowel disease." (PMID 38248332, 2024). "The link of NLRP6 with both neuroinflammation and inflammatory bowel diseases such as Crohn’s disease opens fascinating new research questions in the light of NLRP6 being a cellular homeostasis guard and its potential contribution to these malignancies." (PMID 41266655, 2026). "The activity of multiple inflammasomes has been implicated in inflammatory bowel disease in the regulation of commensal microbiota, while NLRP3, NLRP6, and NLRC4 expression can influence tumor formation." (PMID 34903717, 2021). "During gut dysbiosis, increased numbers of Prevotella were detected during persistent inflammation with HIV infections, metabolic syndrome (insulin-resistance) as well as bowel inflammatory disease induced by NLRP6-inflammation." (PMID 34760910, 2021). "Absence of NLRP6 improved GVHD contrary to models of inflammatory bowel disease (IBD)." (PMID 27965667, 2016).
melanoma (6 papers, 2019 to 2024). A malignant, usually aggressive tumor composed of atypical, neoplastic melanocytes. "By analyzing gene expression profiles of normal skin and melanoma cells, Li and colleagues reported a set of 5 key prognostic, differentially expressed PYR-associated genes (GSDM A, GSDM C, IL18, NLRP6 and AIM2)." (PMID 36674798, 2023). "The immunohistochemical images of IFNGR2, CCL25, IL15, RTP4, and NLRP6 in both normal skin tissue and melanoma tissue confirmed the expression of the GRIPs in CM." (PMID 35492358, 2022). "In addition, an analysis containing NLRP6 gene expression was also used to predict the prognosis and anticancer treatment of cutaneous melanoma, confirming the potential link of NLRP6 in melanoma." (PMID 37415625, 2023). "Accordingly, analysis of anti-PD-1-treated melanoma patients suggested that NLRP6, NLRP7, AIM2, and NLRC4 inflammasomes might contribute to antitumor responses unleashed by checkpoint blockers." (PMID 31085177, 2019). "Compared to HaCaT, melanoma cells showed lower levels of GSDM A, GSDM C and IL18 and higher levels of NLRP6." (PMID 36674798, 2023). "The fundamental constituent of inflammasomes, comprising pyrin, the NOD-like receptor (NLR) family (NLRP1, NLRP3, NLRP6, NLRP9, and NLRC4), and absent in melanoma 2 (AIM2)." (PMID 39125817, 2024).
Salmonella Infections (6 papers, 2018 to 2024). Infections with bacteria of the genus SALMONELLA. "NLRP6 also negatively regulated other cell type function such as hematopoietic and non-hematopoietic cells with increased susceptibility to Listeria and Salmonella infections." (PMID 35694317, 2022). "Also, a recent report showed the specific loss of glutamatergic neurons in the small intestine during Salmonella infection via the Nlrp6/Casp11-dependent mechanism." (PMID 33871822, 2021). "In this context, NLRP6 in both hematopoietic and non-hematopoietic cells increases susceptibility to Listeria and Salmonella infections." (PMID 30248149, 2018). "Recent studies with enteric Salmonella infections concluded that enterocyte IL-18 was not required for bacterial control, but rather that neuronal IL-18 was important and that expression of NLRP6 and ASC in neurons was likely involved in this response." (PMID 33372132, 2021).
Cryptosporidium infection (5 papers, 2021 to 2024). "In contrast, NLRP6-/- mice showed increased parasite shedding and significant susceptibility to Cryptosporidium infection compared with WT control mice." (PMID 36920176, 2023). "We recently reported that an enterocyte intrinsic NLRP6 inflammasome is activated by Cryptosporidium infection leading to release of IL-18." (PMID 35584177, 2022). "The detection of Cryptosporidium sporozoite and trophozoite induces ASC-dependent NLRP6 inflammasome activation, and GSDMD-dependent IL-18 is deficient in NLRP6-deficient mice, leading to the increased susceptibility to Cryptosporidium infection." (PMID 34768828, 2021). "Taken together, these data support a model of innate recognition of Cryptosporidium infection through an NLRP6-dependent and enterocyte-intrinsic inflammasome that leads to the release of IL-18 required for parasite control." (PMID 33372132, 2021). "Finally, we tested the level of secretion of interleukins IL-1β and IL-18, which are involved in the NLRP6 inflammasome, recently described as a key mechanism for enterocyte’s defense against Cryptosporidium infection in a mouse model." (PMID 38189373, 2024). "At this point, the pattern by which NLRP6 detects Cryptosporidium infection is unknown, but a variety of molecular patterns has been suggested to be recognized by NLRP6 in other experimental settings." (PMID 33372132, 2021).